SFRP4 (secreted frizzled related protein 4)
Diseases named in the same sentence as SFRP4 in open-access papers (continued):
Sharing a sentence is not in itself a finding about the gene and the disease.
cancer (continued). "Cytohubba analysis of these genes revealed 13 hub genes, of which MMP13, POSTN, SFRP4, ADAMTS16 and FNDC1 were significantly altered in their expression with CTHRC1 and seen to affect survival across cancers." (PMID 36190948, 2022). "We report the significance of CDKN2A hydroxymethylation by HPV status, as well as many other cancer-related genes, such as CDH1, TIMP3 and SFRP4." (PMID 33203436, 2020). "Expression of cancer stemness-specific genes NANOG and POU5F1 was inhibited in sFRP4 OE cells, whereas sFRP4 SI cells showed elevation in NANOG and POU5F1 gene expression that was much higher than in the untreated U87 control." (PMID 30591679, 2018). "For example, SFRP4, WNT11, FZD2, MYC were highly expressed in cancer tissues which represent the Wnt pathway was activiated and BCL2A1, ICM1, TNFSF14 in NF-κB pathway were highly expressed as well." (PMID 25928635, 2015). "Two members of the secreted frizzled-related protein (SFRP) family, SFRP1 and SFRP4, were more frequently down-regulated in MSI-positive carcinomas compared with MSI-negative carcinomas." (PMID 20368795, 2010). "SFRP4 gene expression had significantly increased fold changes in stroma cancer compared to stroma non-cancer spots (log2FC = 2.098, p = 2.18 × 10−230) and in stroma HG cancer compared to stroma LG cancer spots (log2FC = 2.048, p = 5.44 × 10−175)." (PMID 39511287, 2024). "This analysis revealed significantly higher SFRP4 mRNA levels in cancer compared to non-cancer samples (logFC = 1.59, p = 7.44 × 10−14)." (PMID 39511287, 2024). "Although there was patient-related gene expression variation, of the 34 patients where we had both cancer and non-cancer samples, the majority (n = 31, 91%) had higher SFRP4 gene expression in the cancer samples." (PMID 39511287, 2024). "Comparing samples from relapse-free patients with relapse patients demonstrated significantly higher levels of SFRP4 in the relapse patients when including cancer samples (logFC = 1.13, p = 0.019), but not when including all samples (logFC = 0.87, p = 0.06)." (PMID 39511287, 2024). "We discovered that serum TFF3, Romo-1 and NF-кB levels were significantly higher in patients with EC or OC compared to those without cancer instead of serum SFRP4 levels that were significantly lower in cancer groups compared to the control one." (PMID 35461390, 2022). "Our study in evaluating 1027 matrisome genes across cancers, has identified a novel set of genes (MMP13, FNDC1, SFRP4 and ADAMTS16) that could work with CTHRC1 to regulate cancer progression." (PMID 36190948, 2022). "In a multivariate analysis including various postoperative and prognostic clinico-pathological features, SFRP4 protein expression emerged as an independent prognostic parameter in ERG negative cancers." (PMID 32677026, 2020). "SFRP4 positivity was markedly more frequent in ERG positive (77.4%) than in ERG negative cancers (57.4% p < 0.0001)." (PMID 32677026, 2020). "For 10 of 11 analyzed deletions SFRP4 staining was significantly stronger in deleted than in non-deleted cancers." (PMID 32677026, 2020). "For most surrogate peptides measured, the cancer urine showed higher median L/H values than non-cancer urine; while for several others (CRISP3, CXL14, IL24 and SFRP4), a lower or equal median L/H value in cancer vs. non-cancer was found." (PMID 29254211, 2017). "Although the link between oxidative stress and the regulation of sFRP-4 expression has not been reported to date, sFRP-4 gene expression has been shown as controlled by an epigenetic mechanism, especially by cytosine methylation, during cancer progression." (PMID 25036934, 2014). "Although a number of pathways related to cancer, such as PI3k-Akt, HIF-1 among others, were all enriched among the top DEGs in these datasets, Wnt signalling was significantly enriched compared to other pathways, with genes such as SFRP4, MMP7, among others, being involved." (PMID 37466730, 2023).
cancer (continued). "SFRP4 ELISA showed a high patient-to-patient variation of both non-cancer volunteers and GC patients with no overall difference between the two groups (data not shown) suggesting that baseline or preoperative blood SFRP4 levels are not a suitable for diagnosis of GC." (PMID 33277667, 2021). "Indeed a pan-cancer, in silico study suggests that despite their proposed roles as Wnt antagonists SFRP2 and SFRP4 may promote processes such as cellular invasion and metastasis." (PMID 33277667, 2021). "This novel finding introduces a unique variation to the treatment of cancer since we have found inhibiting SFRP4, while not oncocidal, may be considered oncostatic (limiting invasion and potentially metastasis)." (PMID 33277667, 2021). "ROC curve analyses revealed that methylation status of each individual genes could significantly distinguish primary carcinoma from adjacent normal mucosa, as measured by AUC value (DLX6-AS1: 0.941; lnc-DPH5-1: 0.833; lnc-PRSS2-6: 0.913; lnc-RPS12-6: 0.916; lnc-SFRP4-2: 0.830; SOX21-AS1: 0.921)." (PMID 35127488, 2021). "SFRP4 expression was higher in cancer than in non-neoplastic acinar cells." (PMID 32677026, 2020). "SFRP4 up-regulation was strongly linked to TMPRSS2:ERG rearrangement and ERG expression: Strong SFRP4 positivity increased from 5.6% and 6.3% (by IHC and FISH) in ERG negative cancers to 11.2% and 11.7% in ERG positive cancers (p < 0.0001 each)." (PMID 32677026, 2020). "The data of this study suggest, however that SFRP4 protein measurement may result in clinically useful prognostic information in ERG negative cancer." (PMID 32677026, 2020). "Doing a differential expression between the two clusters of cancer fibroblasts, we found metastatic fibroblasts were found to express higher levels of soluble factors compared to primary fibroblasts including, CXCL12, S100A6, S100A10, SFRP2,SFRP4,IGF1, CXCL14, ANGPTL4 and IL6." (PMID 30383866, 2018). "The independent prediction of membranous SFRP4 expression in the 5 year mortality of gynaecological cancer patients has a factor of 1.8, which means that the chance of dying earlier of cancer is 80% higher if SFRP4 membrane staining is absent in their tumors at the time of diagnosis." (PMID 22363760, 2012). "The strikingly higher SFRP4 expression in ERG positive (>30% with strong SFRP4 positivity) than in ERG negative cancers (<15% with strong SFRP4 positivity) could be explained by the transcriptional activation of ERG and its direct target EZH2, known reported as the upstream regulator of SFRP4." (PMID 32677026, 2020). "SFRP4 belongs to the few biomarkers, which were found to be prognostic in either ERG positive or ERG negative cancers but not in both groups." (PMID 32677026, 2020).
cardiovascular diseases (4 papers, 2014 to 2024). "Secreted frizzled-related protein 4 (SFRP4) is a secreted glycoprotein that has been linked to a variety of cardiovascular diseases." (PMID 38397878, 2024). "Secreted frizzled related protein 4 (SFRP4), a member of the SFRPs family, contributes to a significant function in metabolic and cardiovascular diseases." (PMID 37143778, 2023). "SFRP4 is known to be involved in cardiac development and various cardiovascular diseases." (PMID 38077583, 2023). "In addition, the latest research studies found that SFRP4 also plays an important role in the occurrence and development of cardiovascular diseases." (PMID 37143778, 2023).
metabolic disease (4 papers, 2015 to 2025). A congenital disorder (due to inherited enzyme abnormality) or acquired (due to failure of a metabolically important organ) disorder resulting from an abnormal metabolic process. "Only one study has explored the genetic contribution of SFRP4 to metabolic disorders through the identification of genetic variants in body composition." (PMID 38834984, 2024).
adenocarcinoma (3 papers, 2010 to 2021). A common cancer characterized by the presence of malignant glandular cells. "Analysis revealed that the majority of benign and borderline tumours exhibited sFRP4 expression, while adenocarcinomas demonstrated a significantly reduced sFRP4 expression compared to borderline and benign tumours (p < 0.001)." (PMID 23039795, 2012).
heart diseases (1 paper, 2020). "Several SFRP4-targeted genes, such as MYH6, MYH7, TNNT2 and NKX2-5, contributed to different types of heart diseases." (PMID 32423033, 2020).
skeletal dysplasia (1 paper, 2019). Any Mendelian diseases that affects growth and development of the skeleton. "Importantly, skeletal phenotypes were described for Fam20c (non-lethal Raine syndrome), Lrrk1 (osteosclerotic metaphyseal dysplasia), Pappa2 (short stature), Sfrp4 (Pyle's disease), and Slc10a7 (skeletal dysplasia) prior to knowledge of the human skeletal dysplasias when mutated in humans." (PMID 32117046, 2019).
SFRP4 also shares sentences with these, for which no sentence is quoted: infection (8 papers); atrial fibrillation (2); cardiomyopathy (2); esophageal adenocarcinoma (2); Impaired glucose tolerance (2); leukemia (2); liver fibrosis (2); parasitemia (2); rheumatoid arthritis (2); type 1 diabetes (2); X-linked hypophosphatemic rickets (2); adenoma (1); Alzheimer disease (1); anaplastic astrocytoma (1); anemia (1); Anxiety (1); Arthritis (1); asthma (1); autosomal dominant hypophosphatemic rickets (1); Bardet-Biedl syndrome (1); Barrett’s oesophagus (1); benign tumours (1); biliary atresia (1); bladder cancers (1); bone disorder (1); calcification (1); carcinosarcoma (1); chronic lymphocytic leukemia (1); coronary atherosclerosis (1); COVID-19 (1).
A further 36 diseases each share a sentence with SFRP4 in 1 paper.